TFAM (transcription factor A, mitochondrial)
Diseases named in the same sentence as TFAM in open-access papers (continued):
Sharing a sentence is not in itself a finding about the gene and the disease.
Obesity (26 papers, 2011 to 2025). Accumulation of substantial excess body fat. "If this is the case, TFAM expression in obese children is exceedingly likely to be lower than in normal, potentially weakening the function of the TFAM gene and ultimately promoting obesity." (PMID 38505098, 2024). "TFAM deletion in mutant mice induces obesity and diabetes, probably due to a remodelling of the respiratory chain through the downregulation of multiple proteins involved in oxidative phosphorylation." (PMID 35883794, 2022). "TFAM is required to begin mtDNA transcription and maintain mtDNA stability; however, animals with adipose tissue-specific TFAM deletion exhibit favourable metabolic benefits and prevent diet-induced obesity and insulin resistance." (PMID 36457729, 2022). "It was reported that the inactivation of adipocyte TFAM gene protected the knockout mice from obesity and insulin resistance in the dietary obesity model." (PMID 34987473, 2021). "The major regulators of mitochondrial biogenesis and oxidative metabolism include SIRT1, PGC-1α, and TFAM which have been involved in the development of obesity-mediated IR." (PMID 34889901, 2021). "Adipose specific deletion of TFAM has been shown to result in protection against obesity and insulin resistance while adiponectin-TFAM-knockout mice were resistant to diet-induced weight gain but suffered from various metabolic abnormalities." (PMID 31798691, 2019). "Further exploration of the relationship between CpG-cg05831083 methylation and Vitamin D could contribute to a better understanding of the roles of TFAM and Vitamin D in the occurrence and progression of obesity." (PMID 38505098, 2024). "TFAM deletion in the adipose tissue has been reported to increase energy expenditure through decreased complex I activity and increased uncoupling and protect mice against obesity and insulin resistance." (PMID 35955761, 2022). "Transplantation models of TFAM-expressing brown adipocytes could mimic the phenotype of TFAM TgTg mice, and proving their anti-obesity effect." (PMID 36046191, 2022). "Moreover, knock-out (KO) of mouse transcription factor A mitochondrial (TFAM), a transcription factor required for mitochondrial DNA expression and maintenance protects mice from age and diet-induced obesity and insulin resistance." (PMID 35115503, 2022). "We then evaluated the independent anti-obesity ability of TFAM-overexpression in brown adipocytes." (PMID 36046191, 2022). "TFAM deletion in adipose tissue increases mitochondrial oxidation, with positive metabolic effects, suggesting regulation of adipose tissue mitochondria may be a therapeutic target for obesity treatment." (PMID 38779771, 2024). "Their findings indicate TFAM could play a role in regulating the occurrence of obesity." (PMID 38505098, 2024). "Maternal diet-induced obesity leads to increased mitochondrial potential, mtDNA content, and mitochondrial biogenesis in matured mouse oocytes, which was verified by the upregulation of mitochondrial transcription factor A (TFAM) and nuclear respiratory factor 1 (NRF1) transcripts." (PMID 36932444, 2023). "Furthermore, TFAM‐transgenic mice fed a high‐fat diet did not experience an obesity‐linked reduction in glucose uptake, mitochondrial biogenesis and mineralization in osteoblasts." (PMID 36054692, 2022). "The analysis of the methylation levels of CpG-cg05831083 and CpG-cg14926485 in both obese and normal groups will help us understand the role of epigenetic changes in TFAM and PIEZO1 in obesity." (PMID 38505098, 2024). "Relative mRNA content of protein phosphatase 2 regulatory subunit B gamma (PPP2R5C) and transcription factor A, mitochondrial (TFAM) in VAT of lean (white) and persons with obesity (gray) via qRT-PCR." (PMID 31798691, 2019). "The specific CpG sites, CpG-cg05831083 within TFAM and CpG-cg14926485 within PIEZO1 may serve as the potential biomarkers for diagnosing, treating, and preventing childhood simple obesity." (PMID 38505098, 2024).
Obesity (continued). "To investigate the anti-obesity mechanism of PD, we examined the expression of thermogenic proteins PRDM16 and UCP1, mitochondrial biosynthesis-related protein PGC-1α, TFAM and cAMP pathway related protein P-CREB in adipose tissue after (20R)-panaxadiol administration." (PMID 36909162, 2023). "A 2.33-fold TFAM expression may be appropriate to elicit higher mitochondrial activity leading to BAT activity, phenotypic obesity resistance, and general metabolic improvement." (PMID 36046191, 2022). "Our findings showed that mitochondrial transcription factor A (TFAM) homozygous transgenic (TgTg) mice had highly activated brown adipocytes and increased expression of oxidative phosphorylation, leading to resistance to obesity." (PMID 36046191, 2022). "The DNM1L, MFN2, and TFAM gene expression levels in GO and SAT responsible for regulating mitochondrial dynamics were increased in obese patients without T2DM, and DNM1L and TFAM proteins production were unbalanced in patients with obesity and T2DM." (PMID 34572446, 2021). "There are reports showing that TFAM deletion in adipose tissue and overexpression in skeletal muscle increased mitochondrial function through remodeling the OXPHOS complexes heterogeneously, exhibited anti-obesity effects, and improved general metabolic improvement." (PMID 36046191, 2022). "UCP1, PPARG coactivator 1 alpha (PPARGC1A), transcription factor A, mitochondrial (TFAM), T-box transcription factor 1 (TBX1), and solute carrier family 27 member 1 (SLC27A1) expression was assayed in SAT and VAT samples, obtained during sleeve gastrectomy from 62 patients with obesity." (PMID 31440209, 2019). "Additionally, due to a lack of redundant samples, direct links between methylation and gene expression for TFAM and PIEZO1 in obesity and normal groups could not be established." (PMID 38505098, 2024).
colorectal cancer (25 papers, 2013 to 2026). A primary or metastatic malignant neoplasm that affects the colon or rectum. "Reduced TFAM expression has also been linked to tumor progression in colorectal cancer, chemoresistance in ovarian carcinoma, invasion in melanoma, and metastatic potential in pancreatic ductal adenocarcinoma." (PMID 41226485, 2025). "Here, we investigated the effect of TFAM deficiency on mtDNA and tumorigenic properties in the human colorectal cancer cell line SW480." (PMID 39580766, 2024). "In total, 7 out of 203 BioCarta pathways were significantly enriched in TFAM-deficient compared to control colorectal cancer cells (false discovery rate (FDR) < 0.25; nominal p-value < 0.01)." (PMID 39580766, 2024). "In the present study we found that TFAM deficiency leads to decreased mtDNA levels in the colorectal cancer cell line SW480 and reduced expression of mtDNA-encoded and OXPHOS-related genes." (PMID 39580766, 2024). "In summary, our study reveals that TFAM deficiency in colorectal cancer cells leads to a decrease in mtDNA levels, accompanied by downregulated expression of mtDNA-encoded and oxidative phosphorylation-related genes." (PMID 39580766, 2024). "In this regard, heterozygous TFAM mutations associated with mtDNA depletion were reported in some colorectal cancers." (PMID 29137431, 2017). "TFAM, packing whole mtDNA, is essential to maintenance and transcription of mtDNA, whose mutation is also found to be associated to some colorectal cancer." (PMID 27732955, 2016). "A previous study demonstrated that TFAM in the colorectal carcinoma cell line RKO carrying a TFAM truncating mutation suppressed cell proliferation and inhibited RKO cell-induced xenograft tumor growth." (PMID 24137381, 2013). "Interestingly, total mRNA expression profiling revealed upregulation of the cell cycle inhibitor CDKN1A/p21 in TFAM-deficient colorectal cancer cells." (PMID 39580766, 2024). "Using quantitative PCR we could confirm that the expression of CDKN1A/p21 was 8–25 fold-changes higher in TFAM-deficient colorectal cancer cells when compared to the control (p ≤ 0.05)." (PMID 39580766, 2024). "For example, nuclear-encoded mitochondrial transcription factor A (TFAM) truncation arising from frameshift mutations in a coding mononucleotide repeat of the gene in colorectal cancer cell lines resulted in mitochondrial instability and reduced mitochondrial copy number." (PMID 29164061, 2017). "TFAM high expression is associated with poor outcome for colorectal cancer patients." (PMID 26820294, 2016). "In addition, mutation of the mitochondrial transcription factor A (TFAM) in some colorectal cancers was associated with mtDNA depletion, while its overexpression promoted cell proliferation." (PMID 26977249, 2016). "Taken together, it provided strong evidence that SIRT6 and TFAM play critical roles in the development and progression of colorectal cancer." (PMID 41362737, 2026). "In conclusion, the results demonstrated that SIRT6 inhibits TFAM, leading to mitochondrial dysfunction and inducing mitophagy, ultimately suppressing colorectal cancer growth, which were validated in vivo using a mouse xenograft tumor model." (PMID 41362737, 2026). "Downregulating TFAM in colorectal cancer can also downregulate E-cadherin, vimentin, and snail proteins." (PMID 39927160, 2025). "In cell line studies, TFAM knockdown has been shown to reduce migration and/or invasion in esophageal cancer cells, colorectal cancer cells and lung cancer cells." (PMID 41398603, 2025). "Next we were interested in functional consequences of TFAM downregulation in colorectal cancer cells." (PMID 39580766, 2024). "Our results suggest that TFAM-induced changes of the mitochondrial genome lead to upregulated CDKN1A/p21 expression in colorectal cancer cells identifying p21 as a new possible linker between mitochondria and nucleus." (PMID 39580766, 2024).
colorectal cancer (continued). "Because the colorectal cancer cell line SW480 displays a triploid karyotype, we were only able to isolate clones with two disrupted TFAM alleles and one wild-type allele." (PMID 39580766, 2024). "Silencing TFAM expression in colorectal cancer mediates metabolic reprogramming, inducing α-ketoglutarate (α-KG)-mediated inhibition of the Wnt/β-catenin signaling pathway, thus suppressing tumor initiation." (PMID 38589371, 2024). "In colorectal cancer, increased expression of MCU leads to enhanced uptake of mitochondrial Ca2+, promoting mitochondrial biogenesis by inhibiting TFAM phosphorylation, ultimately accelerating the proliferation of colorectal cancer cells." (PMID 39164792, 2024). "TFAM expression was stably downregulated in the colorectal cancer cell line SW480 using the CRISPR-Cas9 approach." (PMID 39580766, 2024). "Among them, our recent study has demonstrated that upregulated MCU enhances mitochondrial calcium uptake to promote mitochondrial biogenesis and colorectal cancer growth by suppressing phosphorylation of mitochondrial transcription factor A (TFAM)." (PMID 34235078, 2021). "There is a limited number of research available discussing the relationship between TFAM expression and the outcome of colorectal cancer." (PMID 27732955, 2016). "However, though it has been observed that TFAM is associated with the prognosis of patients with colorectal cancer, not much has been done to investigate whether there is a role of TFAM in the development of colorectal cancer." (PMID 27732955, 2016). "The outcomes of colorectal cancer patients whose tumor tissues had high expression of TFAM were worse than those of patients who had low TFAM expression in tumor tissues." (PMID 26820294, 2016). "Our research aims to clarify the core role of SIRT6 in metabolic regulation in colorectal cancer, uncover its anti-cancer mechanisms, identifying TFAM as a promising therapeutic target and provide theoretical support for developing targeted therapeutic strategies based on SIRT6." (PMID 41362737, 2026). "This study aims to investigate whether and how SIRT6 induces mitochondrial dysfunction through the regulation of TFAM, leading to mitophagy, and consequently inhibiting colorectal cancer growth." (PMID 41362737, 2026). "In future, it might be interesting to explore the consequences of TFAM expression in colorectal cancer samples on clinicopathological features." (PMID 39580766, 2024). "While the exact mechanism remains unclear, our findings provide insights into the intricate regulation of mtDNA in colorectal cancer and underscore the significance of TFAM in modulating tumorigenic properties." (PMID 39580766, 2024). "Furthermore, we showed that TEFM promoted HCC metastasis by inducing EMT, which is consistent with another study of TFAM in the promotion of colorectal cancer (CRC) cells." (PMID 33771980, 2021). "In the present study, the regulatory effects of mitochondrial Ca2+ on mitochondrial PDE2/cAMP/PKA axis and the phosphorylation of TFAM, as well as the growth of colorectal cancer cells with MCU overexpression and knockdown were systematically investigated both in vitro and in vivo." (PMID 34235078, 2021).
colorectal cancer (continued). "It proposes that SIRT6 regulates TFAM, leading to mitochondrial dysfunction and the induction of mitophagy, which suppresses tumor progression and may provide a potential therapeutic strategy for targeting colorectal cancer." (PMID 41362737, 2026). "However, the role of TFAM in the tumorigenesis of colorectal cancer cells remains unknown." (PMID 39580766, 2024). "In colorectal cancer, MCU-induced mitochondrial Ca2+ uptake promotes mitochondrial biogenesis and tumour growth through mitochondrial transcription factor A (TFAM) and nuclear factor kappa-light-chain-enhancer of activated B cells (NF-κB)." (PMID 35490194, 2022). "The expression of TFAM was shown to be correlated to the tumor size of HCC, one feature of TNM, though it was reported to be correlated to TNM stage in astrocytomas, colorectal cancer, and non-small cell lung cancer." (PMID 29137431, 2017). "Further, SIRT6 and TFAM were overexpressed or knocked down in HCT116 cells, and scratch assays and EDU cell proliferation assays demonstrated that SIRT6 inhibits both the migration and proliferation of colorectal cancer cells, while TFAM promotes these processes." (PMID 41362737, 2026). "Colorectal cancer cells increase Ca2+ uptake, which activates phosphodiesterase 2 (PDE2) and inhibits the activity of mitochondrial protein kinase A (PKA), leading to the stabilization of TFAM accumulation in mitochondria and promoting colorectal cancer cell proliferation." (PMID 38589371, 2024). "We knocked down TFAM to decrease the mtDNA copy number in several human cancer cell lines, including esophageal squamous cell carcinoma (ESCC), renal cell carcinoma (RCC), colorectal cancer (CRC), and non-small cell lung cancer (NSCLC) as well as GAC in the current study." (PMID 35163779, 2022).